PCNA (proliferating cell nuclear antigen)
Diseases named in the same sentence as PCNA in open-access papers (continued):
Sharing a sentence is not in itself a finding about the gene and the disease.
tumor (continued). "Roniciclib treatment was able to decrease levels of proliferating cell nuclear antigen (PCNA) in TT tumors as compared with the untreated control tumor, indicating cell proliferation inhibition." (PMID 29963260, 2018). "Immunochemical staining of proliferating cell nuclear antigen of tumor tissues indicated the in vivo cell proliferation activities in which the number of PCNA‐positive cells was significantly lower in the PEG/Fe‐LDH group compared with the controls." (PMID 30479938, 2018). "Meanwhile, miR-144-3p, TGF-α and autophagy-related protein and proliferating cell nuclear antigen ki67 were determined in tumor tissues from nude mice with cisplatin treatment." (PMID 30540564, 2018). "We next assessed classical tumour proliferation proteins, including PCNA, c‐myc, cyclin‐A1 and cyclin‐D1, by western blot." (PMID 29435409, 2018). "Immunohistochemistry was performed in tumor tissues derived from each group to measure cell proliferation by PCNA staining." (PMID 30018975, 2018). "131I-5-IPN treatment was associated with reduction of expression of proliferating cell nuclear antigen (PCNA) and Ki67 and cell cycle blockage in G2/M phase in tumor tissues." (PMID 30537980, 2018). "The S-phase marker PCNA showed a remarkable ~ 18-fold elevation in the primary tumor and ~ 25-fold in the subcutaneous tumor compared to the normal tissue indicating their increased proliferation." (PMID 29415661, 2018). "High aTaCC values for cofilin‐1, IL‐32, PCNA, syntenin‐1, and ribophorin‐2 suggested that these proteins were best represented with highest sequence coverage in the tumor immunopeptidomes in this cohort." (PMID 29786170, 2018). "Immunohistochemistry (IHC) for PCNA showed decreased proliferation in the rhein‐treated tumours as compared to control." (PMID 29024409, 2018). "In contrast, IL-6Rα-deficient tumours had less PCNA immunoreactivity compared with control tumours, whereas tumours from HFD-fed control mice had increased PCNA levels indicative of increased proliferation compared with NCD-fed controls." (PMID 29695802, 2018). "Significantly reduced expression of PCNA was observed in the tumour sections from mice that were treated with 12.5 mg/kg escitalopram oxalate relative to those that were treated with PBS or 2.5 mg/kg escitalopram oxalate." (PMID 29105282, 2018). "PEPCK1 showed a significantly inhibitory effect on Huh7 xenograft tumour growth, with a clear decrease of Ki67 and PCNA levels." (PMID 28240261, 2017). "In addition, because BER imbalance may modulate cell survival in a replication-dependent manner, we assessed whether overexpression of BER proteins, notably MPG, was associated with higher tumour proliferation by examining proliferating cell nuclear antigen (PCNA) expression in our samples." (PMID 28903334, 2017). "Immunohistochemical analyses revealed that the number of proliferating cell nuclear antigen (PCNA)-positive tumour cells was significantly reduced in Yamato-SS xenograft tumours treated with TAS-115." (PMID 28511645, 2017). "HCC827/ER xenograft tumor tissues isolated from mice treated with MTE combined with either erlotinib or gefitinib demonstrated remarkably decreased PCNA expressions." (PMID 28915640, 2017). "Tumor antigens play an important role in tumor occurrence, development, and dispersal process, of which PCNA is the most important." (PMID 29019895, 2017). "In line with the observed increase in tumor growth of shCav1 PC3-derived tumors we further detected an increased immunoreactivity to the universal proliferation marker proliferating cell nuclear antigen (Pcna) in these tumors." (PMID 28112237, 2017). "Consistent with the in vitro data, a decrease in the rate of PCNA‐positive tumor cells and an increase in that of cleaved caspase‐3‐positive cells and melanin‐positive cells were observed in trabectedin‐treated CCS xenograft tumors." (PMID 28745431, 2017).
tumor (continued). "PCNA staining showed that CRNDE knockdown obviously reduced the proportion of proliferating (PCNA+) tumor cells." (PMID 28178668, 2017). "Western blotting results showed that DISC1 and PCNA (a cancer cell proliferation marker) levels were higher in NSCLC tissues than in paired adjacent non-tumor tissues, and exhibited similar expression patterns." (PMID 29029423, 2017). "Tumor sections of each group were stained with anti-PCNA antibody and TUNEL reagent in order to evaluate proliferation and apoptosis rate." (PMID 28060755, 2017). "After 11-KT treatment, in both male and female krasV12 fish the PCNA-positive cells increased significantly, suggesting that the androgen 11-KT enhanced tumor cell proliferation." (PMID 28117409, 2017). "A Nur77 deficiency significantly facilitated the proliferation of tumour cells in the analysis of Ki67 and PCNA in these tumour samples." (PMID 28240261, 2017). "We observed that there were fewer PCNA-positive cells (brown) in tumor tissues from DESI2 or IP10 group mice than those in control groups." (PMID 28915590, 2017). "What’s more, metapristone inhibited the growth of NSCLC xenografts in BALB/c nude mice through decreasing the expression of tumor growth biomarkers PCNA and EGFR." (PMID 29108234, 2017). "Treatment with TAS-115 also resulted in a significant reduction in PCNA-positive tumour cells and MVD in SYO-1 xenografts." (PMID 28511645, 2017). "There was an increase in cleaved caspase-3 and γH2AX as well as a reduction in positive staining for PCNA, a marker for cellular proliferation, in the Compound A treated group compared to the control group in the tumor sections." (PMID 28439094, 2017). "Immunohistochemical analysis on tumor samples showed that proliferating cell nuclear antigen (PCNA), an indicator of cell proliferation, decreased substantially in tumors treated with Asc." (PMID 29215048, 2017). "Upregulated PCNA gene expression was also detected in tumor cells incubated with 5-FU chemotherapy under normothermic condition (72 hours at 37°C: FD 4.6) (top)." (PMID 29403306, 2017). "Downregulation of miR‐141 expression correlated with tumor stage, lymph node involvement, and expressions of PCNA, Ki67, and HER2." (PMID 28220627, 2017). "In determined areas of GBM samples, β3-specific fluorescence was brighter at the tumor front decreasing gradually to the interior; thus, the ratio β3/PCNA in these areas was higher in the front and lower within the tumor." (PMID 29117147, 2017). "Results show that the RNF2 knockdown tumor tissue had decreased PCNA level while increased cleaved caspase-3 level than the control tissues." (PMID 28029659, 2017). "Immunohistochemical staining further confirmed that MBZ-treated tumor cells exhibited significantly decreased or diminished expression of cell proliferation marker PCNA, which was shown highly expressed in the control group." (PMID 28099902, 2017). "In the present study, we found that the protein expression of PCNA was significantly lower in the treated tumour samples than in the control." (PMID 28562655, 2017). "Immunohistochemical staining showed that inhibition of both PCNA and Ki67 expressions in excised tumor tissues of metformin-treated mice compared to control." (PMID 28465536, 2017). "Tumor cells infiltrating renal interstitium had nuclei stained positive for PCNA antibody, were arranged either isolated or grouped, and in some areas resembled cartilaginous tissue surrounded by dense periodic acid-Schiff (PAS) reactive extracellular matrix." (PMID 28845162, 2017). "Proliferation of tumor cells also increased in tumors of the Pre-IH group, as demonstrated by up-regulation of the proliferating cell nuclear antigen (PCNA)." (PMID 28977888, 2017). "Regarding the mechanism of action of MDA and 3α-OH MDA, our findings indicate that the intraperitoneal administration of these triterpenes decreased the levels of the proliferation markers PCNA and Ki-67 in the tumor tissues." (PMID 28878179, 2017).
tumor (continued). "Immunohistochemistry (IHC) studies on tumor tissues demonstrated that the expression levels of the proliferation markers PCNA and Ki-67 were significantly lower in the SW620/miR-15bOE tumors than in the control." (PMID 28646148, 2017). "Consistent with the defect in the DDR apparatus in this mouse model, cells in tumor-free brain areas remained devoid of PCNA foci." (PMID 28832631, 2017). "A larger percentage of NeuT tumour cells were positive for the proliferation marker PCNA, compared to p140-NeuT tumour cells." (PMID 28300085, 2017). "Remarkably, proliferation markers, PCNA and Ki-67, were induced in these tumor cells exposed to chemotherapy which was in case of PCNA confirmed in peritoneal tumor tissues after clinical HIPEC procedures." (PMID 29403306, 2017). "Consistent MIB-1 detection in tumor tissues makes it a better proliferation marker than proliferating cell nuclear antigen (PCNA)." (PMID 29312841, 2017). "Our results showed that the decrease in the levels of the proliferation markers PCNA and Ki-67 as well as the increase in cell death by apoptosis are related to the tumor growth inhibition induced by MDA and 3α-OH MDA in a mouse xenograft model." (PMID 28878179, 2017). "Immunohistochemistry (IHC) demonstrated that Tan IIA significantly inhibited Ki67 and PCNA expression in the tumor specimens." (PMID 28106052, 2017). "Animals treated with Nintedanib in tumor development grades (8 and 12 weeks of age) and sacrificed immediately, showed a decrease in PCNA immunolabeling in the TN12 and TN16 groups." (PMID 28499383, 2017). "Tumor cell proliferation was evaluated by PCNA staining, DNA damage by P-H2Ax foci formation and apoptosis by TUNEL staining in combination-treated mice and compared to both controls and single agents (0.05 mg/kg trabectedin and 25 mg/kg olaparib)." (PMID 28454547, 2017). "The tumor proliferation markers, Ki67 and PCNA, were suppressed and apoptosis by TUNEL assay was activated respectively." (PMID 28106052, 2017). "The expression of the proliferating marker PCNA (Acts as a scaffold to recruit protein involved in DNA replication and repair) for tumor development was also significantly down regulated in the cells treated with both RES and DTX." (PMID 28212547, 2017). "Proliferation markers (Ki-67 and PCNA) were determined and the positive correlation between PCNA and tumor grade (r = 0.8247; p < 0.001) was demonstrated, as opposed to Ki-67." (PMID 28651614, 2017). "We further examined the expression of E-cadherin, proliferating cell nuclear antigen (PCNA) and Beclin-1 in the xenograft tumor tissue specimens." (PMID 28176874, 2017). "Pharmacologic inhibition of HO-1 with ZnPP also reduced the CA15-3 expression and suppressed the tumor cell proliferation as evidenced by decreased expression of proliferating cell nuclear antigen (PCNA)." (PMID 27438141, 2017). "The evaluation of PCNA expression is significant in terms of the determination of malignancy, metastasis and tumour grade." (PMID 28562655, 2017). "When analyzing tumor tissue lysates (at Week-7), we showed that DIgR2 siRNA and 5-FU synergistically downregulated growth marker proteins, Ki-67 and proliferating cell nuclear antigen (PCNA) (three sets of blot data were quantified)." (PMID 28903397, 2017). "Although its expression was known to be restricted to the nucleus, PCNA is recruited by tumour cells to cell synapses with NK cells." (PMID 28145491, 2017). "Tumor antigens play an important role in tumor occurrence, development, and metastasis and among these, PCNA is one of the most important." (PMID 29019895, 2017). "PCNA, the expression of which is elevated in proliferating cells and in most malignant tumor cells, is commonly used as a proliferative/malignancy biomarker in cancer." (PMID 28422726, 2017).
tumor (continued). "After 18 days of implantation, the mice injected with HONE1-EBV-miR-3188 and SUNE1-miR-3188 cells had smaller tumour burdens and displayed lower expression of Ki67 and proliferating cell nuclear antigen (PCNA) in tumour tissues relative to controls." (PMID 27095304, 2016). "The expression of two tumor proliferation factors, proliferating cell nuclear antigen (PCNA) and ki67 were also detected." (PMID 26846780, 2016). "To further manifest the effect of NMHC on tumor development, we assessed tumor cell proliferation and apoptosis in vivo, and detected decreased PCNA and enhanced cleaved Caspase-3 expression from the compound-treated tumors." (PMID 27211848, 2016). "In tumor cells, activation of Stat3 involve in regulation of anti-apoptotic genes and cell cycle regulators, such as Bcl-xL, Bcl-2, Cyclin D1 and PCNA." (PMID 27563884, 2016). "IHC staining revealed that tumor xenografts with Barx2 knocked down showed higher expression of the cell proliferation markers Ki-67 and PCNA than controls, consistent with results of in vitro assays." (PMID 27533254, 2016). "Further verified by the higher expression of cell proliferation biomarkers Ki-67 and PCNA with IHC staining of the tumor xenografts, we demonstrated that Barx2 inhibits GC cell proliferation in vitro and in vivo." (PMID 27533254, 2016). "The crucial role of PCNA in cellular proliferation supports its frequent use as a marker of tumor cell proliferation." (PMID 27614686, 2016). "Taken together, our data indicated that SL4 retarded tumor growth in vivo by decreasing the expression level of PCNA and cdc25C, and increasing the expression of p21." (PMID 27819344, 2016). "Microscopic examination of PCNA-stained tumor sections shows a decrease in PCNA-positive cells in AED-1/MTDH siRNA-treated rats as compared with the untreated controls." (PMID 26909607, 2016). "The reduction in tumor growth in the siRNA-PA28α tumors was accompanied by a significant reduction of PCNA expression (58 % reduction by PCNA staining) comparing to that of the siRNA-Control tumors." (PMID 26892607, 2016). "The tumor growth suppression was associated with decreased cell proliferation as revealed by reduced expression of proliferating cell nuclear antigen (PCNA) in withaferin-A-treated xenograft tumor as compared with that of control animals." (PMID 26959007, 2016). "Ki67 and PCNA, representing proliferative activities of the tumor cells, were also inhibited by sgp130 in the treated group." (PMID 27080032, 2016). "In groups treated with stem cells expressing CD and/or IFN-β genes, expression of the PCNA protein decreased significantly in tumor burden of the brain, with a greater reduction occurring in the HB1.F3.CD.IFN-β cells treated group." (PMID 26716512, 2016). "Tumor sections from DMBA control rats showed an abundance of PCNA-positive cells, indicating extensive cell proliferation." (PMID 26699876, 2016). "In contrast, PCNA positive tumor cells were remarkably increased in pERK1/2 strongly positive adenocarcinomas." (PMID 26864819, 2016). "Since PCNA has been widely recognized as a tumor marker for cancer progression and poor patient prognosis, SETD8-dependent PCNA methylation is likely to promote tumorigenesis." (PMID 27688818, 2016). "CDDO-Me also decreased the proliferation and increased the cell death of tumor cells, as assessed by PCNA and TUNEL staining." (PMID 27780924, 2016). "Knockdown of PTX3 by lentiviral vector-mediated PTX3 shRNA suppressed tumor invasion by inhibiting expression of Akt, NF-κB, proliferating cell nuclear antigen, and MMP-911." (PMID 27377307, 2016). "The cell proliferation rate, as measured by the ratio of Ki-67 and PCNA positive tumor cells, were increased in tumors from the RAP1B-overexpressing group and decreased in tumors from the miR-28-5p-overexpressing group." (PMID 27729617, 2016).
tumor (continued). "Down-regulation of S100A9 inhibited OS cellular proliferation, migration, invasion and cell cycle S phase in vitro and suppressed tumor formation in vivo with the reduction on PCNA and Ki67 proliferation index." (PMID 27020242, 2016). "The tumor cell proliferation rate, as measured by the staining intensity of Ki-67 and PCNA, was increased in tumors from the miR-96-overexpressing group." (PMID 27857177, 2016). "In a xenotransplanted tumor model of human endometrial cancer in nude mice, increased PAX2 expression was observed in tumors with poor cell differentiation, and tumor volume as well as expression of PCNA and Bcl-2 were decreased following knockdown of PAX2." (PMID 27764784, 2016). "Next, immunostaining analysis of the proliferation marker PCNA and Ki67 was performed in resected tumor tissues." (PMID 27121316, 2016). "Treatment significantly lowered PCNA expression, whereas a high level of this antigen expression was observed in vehicle control tumor tissue." (PMID 27003027, 2016). "Concomitant with the results obtained for in vivo tumor growth inhibition, we also observed decreased proliferation as documented by PCNA and Ki-67 immunostaining, and increased apoptosis as documented by decreased Survivin expression within tumor tissues." (PMID 26755649, 2016). "To determine the cell proliferation within tumors, we further performed immunostaining on tumor sections with PCNA antibodies." (PMID 27029190, 2016). "Immunohistochemical staining of tumor tissues showed that there was a decrease in proliferation marker (PCNA) in LV-lncRNA-LET group versus LV-Vector group." (PMID 27896272, 2016). "Histological examination of the tumor tissues revealed the decrease in cell proliferation in the treatment group (as it is evident by decreased staining for proliferation markers PCNA and KI67) and increase in apoptosis (cleaved caspase 3 staining)." (PMID 26881967, 2016). "As expected, we observed a significant increase in PCNA level, a marker for cell proliferation in tumor extracts compared to non-tumor." (PMID 26981776, 2016). "Immunostaining demonstrated that levels of PCNA, a cell proliferation marker, were lower in the bakuchiol-treated A431 tumor groups compared to the vehicle-treated groups." (PMID 26910280, 2016). "Immunohistochemical (IHC) staining also confirmed that tumor xenografts with miR-520g overexpression or downregulation showed higher or lower expression of Ki-67, c-myc, CyclinD1 and PCNA, respectively, than controls." (PMID 27049921, 2016). "While more work is required to reveal yet hidden cross-regulations among members of the replisome, our work unveils a novel tumor suppressor function of p21 dependent on its ability to interact with PCNA." (PMID 27740454, 2016). "PCNA immunohistochemistry on rb1cr2/rbl1cr2 MDKO tadpoles revealed identical proliferation characteristics of the neoplasms." (PMID 27739525, 2016). "The AOM/DSS induced neoplasm resembles human caCRC in several aspects of its molecular pathogenesis, specifically in both increased PCNA and β-catenin expression and nuclear translocation of the latter." (PMID 25897964, 2015). "We further noticed that cell proliferation was also downregulated in tumor samples as reflected by PCNA staining, which is probably due to the inhibition of proliferative pathways such as MET signaling." (PMID 26384345, 2015). "The immunohistochemical analysis of tissue sections was stained with H&E, and proliferating cell nuclear antigen (PCNA) also revealed greater inhibition of tumor growth in IL-32α Tg mice." (PMID 25909160, 2015). "The intensity of PCNA-positive cells was lower in the tumor samples from honokiol-treated animals compared to the tumors from control animals." (PMID 26020804, 2015). "Western blot analysis revealed the down regulation of AKAP4 and PCNA protein in AKAP4 shRNA3 treated tumor lysates as compared to NC shRNA treated tumor lysates." (PMID 26590805, 2015).